OR4D2 (olfactory receptor family 4 subfamily D member 2)
Description:
Odorant receptor.
Synonyms: BC2009; OR17-24
Tractability: Antibody: its Gene Ontology location is reachable by antibodies, with high confidence; UniProt places it where antibodies can reach, with medium confidence; UniProt predicts a signal peptide or a membrane-spanning region.
Gene: Protein-coding gene on chromosome 17 (58,166,982 to 58,171,411, forward strand). Ensembl gene ENSG00000255713.
Subcellular location: Cell membrane
Pathways (Reactome):
Sensory Perception: Expression and translocation of olfactory receptors; Olfactory Signaling Pathway
Gene Ontology:
Molecular function: olfactory receptor activity; G protein-coupled receptor activity
Biological process: detection of chemical stimulus involved in sensory perception of smell; G protein-coupled receptor signaling pathway
Cellular component: plasma membrane; membrane
Genetic constraint (gnomAD): Loss-of-function variants: 11 observed, 15.73 expected, observed/expected ratio (o/e) 0.7, 90% interval 0.44 to 1.16. The upper end of that interval is the gene's LOEUF score, 1.16, which puts it in group 5 of 6, group 1 being the genes least tolerant of losing a copy. Missense variants: 373 observed, 401.19 expected, observed/expected ratio (o/e) 0.93, 90% interval 0.85 to 1.01. Synonymous variants: 151 observed, 158.02 expected, observed/expected ratio (o/e) 0.96, 90% interval 0.84 to 1.09.
Homologues: Orthologues: macaque OR4D2 (94% identical), dog OR4D2C (87% identical), dog OR4D2 (86% identical), rabbit OR4D2 (85% identical), mouse Or4d2b (84% identical), mouse Or4d2 (83% identical), rat Or4d2 (83% identical), rat Or4d2b (83% identical). Paralogues in human: OR4D1 (79% identical), OR4D9 (64% identical), OR4D11 (63% identical), OR4D6 (62% identical), OR4D10 (61% identical), OR4D5 (58% identical), OR4N2 (50% identical), OR4Q3 (50% identical), OR4N5 (50% identical), OR4F4 (49% identical), OR4F5 (49% identical), OR4N4 (48% identical), and 116 more.